KRAS (KRas proto-oncogene, GTPase)
Diseases named in the same sentence as KRAS in open-access papers (continued):
Sharing a sentence is not in itself a finding about the gene and the disease.
pancreatic ductal adenocarcinoma (continued). "It is interesting to consider these results in the context of two recent studies where the combinatorial effect of Palbociclib and MEK inhibitor (Trametinib) was tested in models of KRAS-driven NKX2-1-positive LUAD and in KRAS-driven pancreatic ductal adenocarcinoma (PDAC)." (PMID 33821796, 2021). "In pancreatic ductal adenocarcinoma (PDAC), TP53TG1 works via the miR-96/KRAS axis through directly binding to tumor suppressor miR-96 and preventing miR-96 from binding to its target oncogene KRAS, thus elevating KRAS expression." (PMID 34564314, 2021). "Survival rates for most KRAS-mutated cancers such as non-small cell lung cancer (NSCLC) and pancreatic ductal adenocarcinoma (PDAC) have not significantly improved since the 1970s." (PMID 32194994, 2020). "Unfortunately, no clinically approved KRAS-targeting treatment is available for pancreatic ductal adenocarcinoma as of yet." (PMID 32796566, 2020). "Deltarasin is a recently identified small molecule that can inhibit KRAS–PDEδ interactions by binding to a hydrophobic pocket on PDEδ, resulting in the impairment of cell growth, KRAS activity, and RAS/RAF signaling in human pancreatic ductal adenocarcinoma cell lines." (PMID 29440631, 2018). "Importantly, in KRAS-induced murine tumor models, EGFR signaling is essential for KRAS oncogene-driven pancreatic ductal adenocarcinoma." (PMID 29156578, 2017). "Our results revealed that KRAS is significantly overexpressed in pancreatic ductal adenocarcinoma in comparison to the non-tumor counterpart." (PMID 23425895, 2013). "Moreover, a previous study reports that YAP1’s transcriptional activity is modulated by oncogenic KRAS signaling through the MAPK pathway in pancreatic ductal adenocarcinoma without changing its subcellular location." (PMID 38730733, 2024). "Improvements in chronic peripancreatic adipose tissue inflammation, leptin, hyperinsulinemia, T2DM, KRAS activation, IGF and intestinal microbiome after dietary intervention and bariatric surgery may explain the decreased development of pancreatic ductal adenocarcinoma after bariatric surgery." (PMID 37047163, 2023). "Pancreatic ductal adenocarcinoma (PDAC) is characterized by its unique metabolic properties that are established both in a cell-intrinsic and -extrinsic manner, dictated by oncogenic KRAS signaling and shaped in close interaction with the host cells in the tumor microenvironment." (PMID 36139512, 2022). "Indeed, KRAS mutant but not KRAS wild-type pancreatic ductal adenocarcinoma (PDAC) cancer cells induce CAFs activation through CXCR-2, leading to a nuclear factor-kappa B (NF-κB)-mediated secretion of pro-tumoral cytokines interleukin (IL)-4, IL-10, and IL-13." (PMID 33553157, 2020). "As bone tumors in H2‐c‐fosLTR mice arise from the osteoblastic lineage, we hypothesize that the tumor cell‐intrinsic function of EGFR might be similar to its role in pancreatic ductal adenocarcinoma (PDAC), where EGFR deletion or inhibition was shown to ameliorate KRAS‐driven PDAC." (PMID 30361264, 2018). "Pancreatic ductal adenocarcinoma (PDA) harbors an exceedingly poor prognosis, and is generally considered a therapy-recalcitrant disease due to poor response to conventional chemotherapy coupled with non-actionable genetic drivers (e.g. KRAS mutations)." (PMID 26158861, 2015). "Also arguing against mutant KRAS as a marker of ferroptosis sensitivity, artesunate (ART) was shown to induce ferroptosis in an iron- and ROS-dependent manner in pancreatic ductal adenocarcinoma (PDAC) cell lines irrespective of KRAS status." (PMID 31936571, 2020).
breast cancer (519 papers, 1988 to 2026). A primary or metastatic malignant neoplasm involving the breast. "Studies have shown that estrogen exposure downregulates the expression of tumor suppressor gene RASSF (Ras association domain family) in breast cancer, thereby abolishing the inhibition of oncogene KRAS." (PMID 39865137, 2025). "KRAS plays a critical role in the development of breast cancer and is associated with genetic susceptibility to the disease." (PMID 39702350, 2024). "Ribociclib exhibited higher IC50 values in DLD-1 (PIK3CA/KRAS-mutated) and Caco-2 (PIK3CA/KRAS wild-type) lines (IC50 >15 μM) compared to breast cancer models, though values for the SNUC4 (PIK3CA-mutated) and LS1034 (KRAS-mutated) lines were comparable." (PMID 39769028, 2024). "β3 Integrins have been linked with KRAS to promote fitness and survival of established pancreatic, lung, and breast carcinomas and can promote resistance to EGFR inhibitors." (PMID 38755258, 2024). "We selected PIK3CA, which, like KRAS, is also one of the commonly mutated proto-oncogenes in human cancers—in human breast cancer, it is mutated in 36% of all cases, the highest among mutated proto-oncogenes." (PMID 37172086, 2023). "KRAS mutations are known as very infrequent in triple-negative breast tumors, but in basal breast cancer, KRAS has been shown to promote the mesenchymal features of this aggressive cancer." (PMID 37681908, 2023). "The three most enriched hallmarks associated with the basal-like breast cancers within cluster 1 are “UV-response down”, “KRAS signaling up”, and “Epithelial Mesenchymal Transition”." (PMID 38111531, 2023). "The most prevalent KRAS mutations in breast cancer are G12C/D/V/A mutations, with some of these G12C mutant patients potentially benefitting from treatment with the recently developed sotorasib or adagrasib therapies." (PMID 37805590, 2023). "KRAS mutations affecting codon 12 are reported in human breast cancer and described as putative driver mutations." (PMID 36635367, 2023). "The mutation site (c.35G > T, p.G12V) is the hot spot mutation site of the KRAS gene, which has been reported in a variety of tumors, including breast cancer." (PMID 36737820, 2023). "One study investigated KRAS mutations in ctDNA of 106 HR+/HER2- metastatic breast cancer patients treated with palbociclib plus fulvestrant and found that after 18 months, all patients with KRAS alterations had progressive disease." (PMID 36176758, 2022). "Kirsten rat sarcoma viral oncogene homolog (KRAS) mutations also drive endocrine resistance in breast cancer patients." (PMID 35784388, 2022). "Here we show that increased expression of YB-1 characteristic of poor prognosis breast cancers is associated with elevated KRAS or AKT activity and an activated stress response programme." (PMID 34294889, 2022). "A recent review by Brandao and coworkers critically analyzes clinical trials with PI3K inhibitors and suggests KRAS mutations among potential biomarkers for resistance in PIK3CA-mut breast cancer." (PMID 35719951, 2022). "Extensive studies have shown that KRAS upregulation is associated with various malignancies, including lung adenocarcinoma, ductal carcinoma of the pancreas, colorectal carcinoma, and breast carcinoma." (PMID 35614051, 2022). "Human breast cancers rarely show KRAS and BRAF mutations, whereas mutations in genes that activate the PI3K-Akt pathway have been reported." (PMID 33793658, 2021). "As for the breast cancer samples, the pathway module 8 contained several well-known driver mutations, including KRAS, APC, and ARID1A." (PMID 33819263, 2021).
breast cancer (continued). "Since oncogenic KRAS causes triple-negative mammary tumors, a short administration of Tam is not expected to have any biological effect on the growth and survival of mammary cancer cells." (PMID 34675248, 2021). "For KRAS mutations, the highest clonality was present in pancreatic and biliary cancer, whereas the lowest clonality was present in breast cancer." (PMID 33397889, 2021). "This breast cancer subtype also exhibits a strong activation of RAS/MAP kinase signaling due to amplification of KRAS and BRAF, as well as loss of NF14,10,11." (PMID 34145248, 2021). "Serial plasma cell-free DNA genotyping analyses of 106 ER+ breast cancer patients over the course of treatment with palbociclib and fulvestrant were analyzed, and patients who developed KRAS mutations over time became resistant to palbociclib." (PMID 34830174, 2021). "To compare this unexpected change in YAP expression with another model of human breast cancer with KRAS mutations, we first examined tumors similarly generated in female NRG mice 8 weeks after being injected with KRASG12D-transduced MCF10A cells." (PMID 31772328, 2020). "Deregulation of the KRAS pathway has been genetically implicated in more than 20% of human breast cancers, although oncogenic mutations in KRAS itself have been identified in only about 4% of cases." (PMID 31772328, 2020). "PIK3CA mutant breast cancer cell lines, with additional mutations in KRAS, are shown to confer resistance to inhibition by AZD8835." (PMID 32194423, 2020). "Elevated Ras signaling drives many clinical luminal B cancers and it is associated with poor prognosis; furthermore, KRAS promotes the mesenchymal features of basal-type breast cancer." (PMID 32210163, 2020). "Yet, limited data exist on chemotherapy-resistant breast cancers profiled at the end of therapy, representing a knowledge gap of KRAS mutational rates in that population." (PMID 32634121, 2020). "Analysis of thousands of genetic profiles of human breast cancers revealed an enrichment of KRAS mutations in metastatic breast cancers versus primary breast cancer; however, these mutations were all codon 12 and codon 13 mutations." (PMID 32634121, 2020). "This NAM-induced dephosphorylation of ERK was also observed in human breast cancer MDA-MB-231 cells harboring KRAS mutation." (PMID 32276460, 2020). "To explore the suppressive role of miR-143 associated with KRAS signaling pathways in breast cancer cells, we examined the expression levels of KRAS by western blot analysis and qRT-PCR." (PMID 32370060, 2020). "RAC2 and KRAS are 2 members of the Ras proto-oncogene superfamily, associated with breast cancer tumorigenesis and metastasis." (PMID 31481608, 2019). "The present study showed that KRAS-mutated cells had significantly higher phospho-YB-1 than KRAS wild-type cells, which agreed with the role of KRAS in YB-1 phosphorylation in breast cancer cells." (PMID 31010234, 2019). "Several case control studies have linked the KRAS-variant to increased risk of breast cancer, though the effect appears to be dependent on patient context." (PMID 30897768, 2019). "Conversely, many genes frequently mutated in MPA/DMBA-induced tumors, such as ATR, FAT1, and KRAS, are rarely mutated in breast cancer." (PMID 31366361, 2019). "IL-17 also triggers neutrophil recruitment to tumor sites in 4T1 breast carcinoma, KRAS mutated lung carcinoma, and ovarian carcinoma." (PMID 31474975, 2019). "For example, the highly significant mutations in genes like PIK3CA or KRAS are observed in ~30% of breast cancer patients." (PMID 30374409, 2018). "With respect with breast cancer for instance, KRAS mutation rate in metastatic breast cancer was estimated at approximately 12%." (PMID 28532501, 2017).
breast cancer (continued). "Along the same lines, KRAS mutations were detected in only 2% of luminal A versus 17.4% in luminal B breast cancer, suggesting accumulation of KRAS mutation in more aggressive forms of disease." (PMID 28532501, 2017). "Similar results were obtained with the breast cancer cell line MDA-MB-231 that likewise carries the KRas G13D mutation." (PMID 26051945, 2015). "Although abnormal expression of miRNA and KRAS has been associated with tumorigenesis in human breast cancer, we still know little about how miRNAs act on KRAS." (PMID 26392416, 2015). "As the relevance of KRAS mutations in breast cancer remains elusive, the physiological effects of miR-200c-dependent KRAS silencing were explored in a more relevant cancer type." (PMID 24368337, 2014). "Associations between the KRAS genotype and breast cancer or breast tumor characteristics were assessed using chi-square test and logistic regression models." (PMID 22436609, 2012). "The KRAS-variant was found in 22.7% (n = 5/22) of patients with two separate primary breast cancers and ovarian cancer; 0% (0/12) of BRCA1 patients, 33.3% (1/3) of BRCA2 patients and 57.1% (4/7) of uninformative patients." (PMID 22662244, 2012). "The KRAS variant allele was detected in 17.2% of sporadic breast cancer cases and in 18.2% of all familial cases (10.3% of BRCA carriers - 10.0% of BRCA1 and 11.1% of BRCA2 carriers and in 19.9% of non-BRCA carriers)." (PMID 22436609, 2012). "We aimed to investigate an association of the KRAS variant with sporadic and familial breast cancer and breast tumor characteristics." (PMID 22436609, 2012). "Modification of the effect of HRT use on breast cancer risk by the KRAS variant shown in our study is highly reasonable." (PMID 22436609, 2012). "On the basis of the current evidence, the purpose of our study was to investigate the association of the KRAS variant with sporadic and familial breast cancer risk among Slovenian women." (PMID 22436609, 2012). "We demonstrate that captured CTCs are amenable to biomarker analyses such as HER2 status, qRT-PCR for breast cancer subtype markers, KRAS mutation detection, and EGFR staining by immunofluorescence (IF)." (PMID 20838621, 2010). "Secondly, our findings indicate that captured CTCs are amenable to biomarker analyses such as HER2 status, qRT-PCR for breast cancer subtype markers, KRAS mutation detection, and EGFR staining by IF." (PMID 20838621, 2010). "Studies on the RAS gene family—KRAS, HRAS, and NRAS—have revealed the pivotal role of KRAS mutations in various cancers despite their relatively low frequency in breast cancer, emphasizing the untapped potential for precision treatments targeting this mutation." (PMID 40236954, 2025). "Interestingly, as we identified EMD to mediate nuclear size reduction in PDAC cells downstream of mutant oncogenic KRAS, another study involving breast cancer found that EMD was causal in nuclear size enlargement." (PMID 40493403, 2025). "Moreover, the downregulation of the RAS-GAP RASA1 in a large percentage of breast cancer cases and a small percentage of cases with KRAS mutations suggests that RAS hyperactivity commonly drives breast cancer cases overall." (PMID 38540084, 2024). "A study has identified mutations in the rs9266 gene locus within KRAS, which may be linked to an elevated risk of breast cancer in women." (PMID 39702350, 2024). "Additionally, TNBC patients with KRAS mutations often display resistance to radiation therapy, a key component of breast cancer treatment." (PMID 38571493, 2024). "We suggest that activation of the KRAS or PIK3CA oncogenes or loss of the PTEN suppressor gene may be important for mammary tumor development in dogs." (PMID 36635367, 2023). "We next asked whether the deregulated KRAS activity and associated YB-1 dependence might be elicited in a human breast cancer cell line with less aggressive features of transformation." (PMID 34294889, 2022).
breast cancer (continued). "In this report, we demonstrate the versatile applicability of the new MMTV-Flp strain to manipulate genes in a temporally and spatially controlled manner in the normal mammary gland, in luminal-type mammary tumors that overexpress ERBB2, and in a new KRAS-associated mammary cancer model." (PMID 34675248, 2021). "However, out of all RAS proteins, KRAS is the most frequently mutated RAS protein in breast cancer and is associated with poor prognosis as well as increased rate of metastasis." (PMID 33801965, 2021). "Thus, the prevalence of KRAS codon 61 mutations in breast cancers that have undergone therapeutic selection remains to be determined." (PMID 32634121, 2020). "In addition, we show that YAPS127A-transduction of the human MDA-MB-231 breast cancer cell line (that carry a similar KRAS mutation) enhances their metastatic activity in vivo." (PMID 31772328, 2020). "Given this background, we hypothesized that miR-143 plays a suppressive role in breast cancer development by targeting KRAS and its associated molecules." (PMID 32370060, 2020). "Based on the data obtained using a panel of breast cancer cell lines and effects seen in patient-derived tumor cells, we also identify the subset of breast cancers that will be resistant to treatment, that is TNBCs with KRAS or BRAF mutations, or TNBCs with high MAPK activity." (PMID 32667883, 2020). "Our work has focused on the study of paired breast cancer PDXs before and after the development of chemotherapy resistance to identify targetable, KRAS mutant–associated signaling mechanisms that promote tumor progression and alter the tumor immune microenvironment." (PMID 32634121, 2020). "Here we demonstrate that breast cancer cell lines with oncogenic mutations that activate KRAS or the PI3K pathway fuel proliferation in nutrient-limiting conditions using not just amino acids, but also sugars, lipids, and nucleotides scavenged via macropinocytosis." (PMID 32111826, 2020). "Similarly, Cerne and colleagues reported the association of the KRAS-variant with HER2 overexpression in breast cancer in postmenopausal women." (PMID 30897768, 2019). "Therefore, there is a crucial demand to discover more effective treatments for pancreatic and breast cancers that harbor KRAS mutations." (PMID 30654191, 2019). "This may imply that KRAS-variant status affects HER2 expression in developing breast cancer, which is age dependent." (PMID 30897768, 2019). "Thus, YB-1 downstream of KRAS is constitutively active, as reported in KRAS-mutated breast cancer cells." (PMID 31010234, 2019). "KRAS-variant-associated breast cancer risk appears to be impacted by estrogen withdrawal." (PMID 30897768, 2019). "The analysis of the top 300 up- and down-regulated genes in both mutants and their comparison to luminal and basal/mesenchymal breast cancer gene expression profiles reported previously, associated KRAS G13D with the basal/mesenchymal and KRAS G12D with the luminal breast cancer subtype." (PMID 31681616, 2019). "We also sequenced short fragments of ACTB and HER2 transcripts in a breast cancer tissue, and sequenced codon 12 and 13 of the KRAS transcript to detect a KRAS mutation in rare (one in 1,000) KRAS mutation‐positive cancer cells spiked into a background of KRAS‐negative cells." (PMID 27406789, 2016). "KRAS mutations in mammary tumors from MMTV-p200 CUX1 transgenic mice." (PMID 24618719, 2014).